HDAC5 (histone deacetylase 5)
Diseases named in the same sentence as HDAC5 in open-access papers (continued):
Sharing a sentence is not in itself a finding about the gene and the disease.
metabolic disease (1 paper, 2017). A congenital disorder (due to inherited enzyme abnormality) or acquired (due to failure of a metabolically important organ) disorder resulting from an abnormal metabolic process. "Histone deacetylase 4 (HDAC4) and histone deacetylase 5 (HDAC5) are chromatin remodeling enzymes and critical regulators of muscle oxidative and metabolic function; these genes are coordinately down-regulated in metabolic diseases such as obesity." (PMID 28045116, 2017).
myopathy (1 paper, 2025). A disease of the muscle in which the muscle fibers do not function properly. "Correspondingly, canonical MEF2 target genes linked to myopathy and contractile function, including TNNT2, MYH7, ACTN2, and ACTA1, were also restored upon HDAC5 silencing." (PMID 41283336, 2025).
vascular disorder (1 paper, 2022). A general term used to describe any disease affecting blood vessels]. "Interference of IGF-1 receptor tyrosine kinase and NAD(P)H oxidase mitigated IGF-1 induced HDAC5 phosphorylation, thereby suggesting that HDAC5 phosphorylation is related to NAD(P)H oxidase-induced ROS generation and vascular disorders." (PMID 35529430, 2022).
HDAC5 also shares sentences with these, for which no sentence is quoted: laryngeal squamous cell carcinoma (2 papers); pancreatic neuroendocrine cancer (2); schizophrenia (2); T-cell lymphoma (2); acute kidney injury (1); acute lymphoblastic leukemia (1); anaplastic oligodendroglioma (1); cervical squamous cell carcinoma (1); colorectal (1); colorectal tumours (1); Crohn disease (1); endometrial cancer (1); familial colorectal cancer (1); fibrosarcoma (1); Hepatic steatosis (1); hypertrophy (1); intestinal diseases (1); Kaposi's sarcoma (1); kidney cancer (1); liposarcoma (1); lung disease (1); lymphoma (1); metabolic syndrome (1); mood disorder (1); multiple myeloma (1); Myocardial fibrosis (1); myocardial ischemia (1); neurological disorders (1); oral cancer (1); Parkinson disease (1).
A further 6 diseases each share a sentence with HDAC5 in 1 paper.